TMEM147-AS1 (TMEM147 antisense RNA 1)
Gene: Long non-coding RNA gene on chromosome 19 (35,540,731 to 35,546,029, reverse strand). Ensembl gene ENSG00000236144.
Diseases named in the same sentence as TMEM147-AS1 in open-access papers:
TMEM147-AS1 is named in the same sentence as 1 disease in open-access papers, as found by Europe PMC text mining. Sharing a sentence is not in itself a finding about the gene and the disease. The quoted sentences say what the papers report.
prostatic carcinoma (1 paper, 2023). "TMEM147-AS1 (lncRNA TMEM147 antisense RNA 1) promotes tumorigenesis in prostate cancer by controlling prostatic carcinoma cell invasion and proliferation." (PMID 37891677, 2023).